IL6 (interleukin 6)
Diseases named in the same sentence as IL6 in open-access papers (continued):
Sharing a sentence is not in itself a finding about the gene and the disease.
COVID-19 (continued). "Progression to severe COVID-19 is caused by hyperinflammatory responses characterized by exaggerated activation of myeloid cells, such as neutrophils and monocytes/macrophages, and the overproduction of proinflammatory cytokines, such as TNF, IL-6, and IL-1β6–9,12." (PMID 36941461, 2023). "Both COVID-19 and RA exhibit an excessive immune response and cytokine imbalance, which are caused by the overactivation of T cells (especially Th1 and Th17 cells) that secrete a large number of cytokines, including TNF-α, IL-1β, IL-6, IL-8, IL-17, and GM-CSF, leading to tissue damage." (PMID 37163438, 2023). "Interestingly, the expression of IL-6 has been also elevated in severe COVID-19 patients." (PMID 36830876, 2023). "Moreover, interleukin-6 levels were lower in COVID-19 patients randomized to PCSK9 inhibitors." (PMID 37158917, 2023). "Indeed, corticosteroids, Janus kinase (JAK) inhibitors that block cytokine signaling pathways such as Ruxolitinib (Ruxo) or Baricitinib, the IL-6 antibody Tocilizumab or the IL-1 receptor antagonist Anakinra were found to improve outcome in hospitalized COVID-19 patients." (PMID 37293294, 2023). "Additionally, we documented that convalescent COVID-19 subjects with systemic inflammation and increased serum levels of circulating IL-6 may benefit more in terms of endothelium-dependent vasodilation from a rehabilitation program." (PMID 36983234, 2023). "Similarly, IL-6 levels were also increased in severe COVID-19." (PMID 36673615, 2023). "The aim of the present study was to examine whether Dipeptidyl-peptidase 3 (DPP3) and the inflammatory biomarkers IL-6, CRP, and leucocytes are associated with COVID-19 and able to predict the severity of pulmonary infiltrates in COVID-19 patients versus non-COVID-19 patients." (PMID 37733154, 2023). "However, in newborns of mothers with COVID-19, elevated concentrations of IL-6 (i.e., M = 143 pg/mL) and TNF-α (i.e., M = 103.41 pg/mL) suggest that the babies were suffering from cytokine storms given dosages of the same molecules in the newborns of healthy mothers." (PMID 36979888, 2023). "While COVID-19 mRNA in vaccines is modified to reduce the response by dendritic and TLR expressing cells, some patients with genetic variants in IL-6 may still mount enough of a cytokine response to cause inflammatory damage similar to an actual COVID-19 infection." (PMID 36851240, 2023). "Inappropriate host immune responses in patients with COVID-19 due to the secretion of proinflammatory cytokines such as IL-1, IL-6, and tumor necrosis factor-α (TNFα) could lead to cytokine storms, organ failure, and severe presentations such as pneumonia and neuropsychiatric symptoms." (PMID 37674935, 2023). "Moreover, the level of Il-6 predicts the progression of disease to severe COVID-19." (PMID 37762549, 2023). "Similarly, anti-IL-6 and anti-IL-6R antibodies, such as Sarilumab, Siltuximab and Tocilizumab have been tested for their ability to control virus-induced hyper-inflammation in COVID-19 patients." (PMID 37854602, 2023). "Studies on the interaction of obesity and COVID-19 continue; it is hypothesized that patients with obesity have impaired immune responses and abnormal secretion of proinflammatory cytokines such as interleukin 6 (IL-6), which are already present due to COVID-19, worsening the disease." (PMID 36795723, 2023). "Consequently, reduced miR-451a and increased lncRNA may intensify the cytokine storm induced by IL-6 in COVID-19 patients." (PMID 38140218, 2023). "Hence, the aptamer-functionalized SiNW-FETs may have great potential to be applied in identifying IL-6 levels in patients with severe COVID-19." (PMID 36679421, 2023). "Our study shows that LA-S may be a more sensitive marker for diastolic dysfunction in severe COVID-19, particularly patients at ICU admission with persistent lymphopenia, enriched CM T-cells, and higher IL-6, which may suggest a differential immune trait in cardiac injury COVID-19 patients in ICU." (PMID 36633703, 2023).
COVID-19 (continued). "This implies that in COVID-19 patients, high levels of IL-6 (> 5.186 pg/ml) could be detected." (PMID 37095536, 2023). "COVID-19 is an air-borne disease primarily affecting the respiratory system and inducing a severe inflammatory response, thereby releasing numerous inflammatory mediators such as IL-1, IL-6, and tumor necrosis factor-alpha (TNF-α) leading to cytokine storm which has a detrimental effect." (PMID 36874696, 2023). "In the current study, we found that uPAR expression was decreased in the lung tissue of COVID-19 patients, which could have led to the pro-fibrogenic accumulation of inactive uPA followed by IL-6 and ACE2 upregulation and EMT induction in lung epithelial cells." (PMID 36674896, 2023). "Interestingly, a series of COVID-19 related pathways were significantly enriched by RNAenrich, e.g. human interleukin-4 and interleukin-13 signaling (P = 5.74E-14) (P refers to P.adjust), interleukin-6 signaling (P = 8.64E-04), and so on." (PMID 37399102, 2023). "Furthermore, blood levels of T-cell-associated cytokines, mainly IFN-γ, TNF-α, IL-2, IL-6 and IL-17, increase during severe COVID-19, as opposed to measurements in controls." (PMID 37568402, 2023). "Moreover, it was demonstrated that inhibiting the transduction of IL-6 signals in a therapy by tocilizumab decreased the production of plasminogen activator inhibitor-1 and resolves clinical manifestations in acute form of COVID-19." (PMID 36674665, 2023). "Additionally, IL-6 promotes the proliferation of megakaryocytes and the release of TF, the latter detected in inflamed tissues and in particular in the lungs of patients affected by COVID-19." (PMID 37240292, 2023). "Furthermore, deceased COVID-19 patients had increased infiltration of alveolar macrophages into the lung along with increased expression of several pro-inflammatory mediators such as IL-6." (PMID 36941580, 2023). "Vitamin D inhibits the inflammatory response via IL6 and may mitigate COVID-19 symptoms." (PMID 36890344, 2023). "Given the trial evidence of effectiveness in COVID-19 and supporting genetic evidence in sepsis, we aimed to investigate whether IL-6 downregulation might also lead to improved outcomes in severe malaria and whether this might represent a common target for severe infection." (PMID 36801374, 2023). "Similarly, IL-6 had an AUC of 0.72 (95%CI 0.59 to 0.86, p = 0.0273), with serum concentrations higher than 60 pg/mL having 70% sensitivity (95%CI 44.17% to 87.31%) and 60% specificity (95%CI 47.02% to 71.71%) for COVID-19 mortality." (PMID 37375073, 2023). "Furthermore, the Th17 response in COVID-19 patients instigates pro-inflammatory cytokine IL-17, which employs monocytes and neutrophils to pulmonary circulation and initiates a surge of surplus cytokines such as IL-1β and IL-6." (PMID 37051070, 2023). "Enhanced blood levels of IL-6, C-reactive protein (CRP), D-dimer, and ferritin are indicators of increased cytokine release and may be linked to systemic inflammation and hypoxemic respiratory failure caused by COVID-19." (PMID 37504277, 2023). "In addition, treatment with glucocorticoids in the severe course of COVID-19 decreased IL-6 levels." (PMID 37753372, 2023). "Likewise, severe COVID-19 patients presented an elevated level of blood IL-6." (PMID 36755036, 2023). "However, it is unclear whether comorbidities facilitate an increase in the levels of IL-6 in COVID-19 subjects." (PMID 37095536, 2023). "In patients with severe forms of COVID-19 also a strong relationship between early overexpression of IL-10 and increased serum concentrations of IL-1 receptor antagonist (IL-1RA) and other proinflammatory molecules, including IL-6, IL-8 and C-reactive protein was observed." (PMID 37359549, 2023). "The length and/or severity of COVID-19 may be lessened by modifying IL-6 levels or IL-6’s effects." (PMID 37504277, 2023). "Notably, the cytokine storm in COVID-19 patients is characterized by increased IL-6." (PMID 36768701, 2023).
COVID-19 (continued). "Therefore, under the inflammatory conditions brought on by COVID-19, high levels of IL-1, IL-6, and IL-23 may promote the downregulation of FOXP3, resulting in decreased functionality of Tregs." (PMID 36992283, 2023). "Based on the results of the in vivo COVID-19 cytokine storm study, we focused on the IL-1β, IL-2, IL-6, TNFα, IL-4, and IL-10 molecular pathways as the key elements of the inflammatory response in order to identify the molecular mechanisms of peptidergic regulation of the cytokine storm in COVID-19." (PMID 37686182, 2023). "Importantly, ORI could significantly suppress mRNA expression and secretion of IL-6, which is one of crucial cytokines contributing to the “cytokine storm” of the patients with COVID-19." (PMID 37090710, 2023). "Anti-interleukin-6 (IL-6) monoclonal antibodies may mitigate COVID-19’s inflammatory storm." (PMID 38023988, 2023). "We suggested that Gal-9 could be cleaved as soon as its release into blood in severe conditions but not the recovery phase by TCZ treatment, implying that inhibition of the IL-6 signaling cascade in severe COVID-19 may enhance the subsidence of Gal-9 proteolysis." (PMID 36835000, 2023). "In agreement, in COVID-19 patients, a strong association has been documented between the severity of infection with more severe-to-lethal outcomes and the presence of the immunosenescence phenotype with a high level of the Neutrophils-to-Lymphocytes Ratio (NLR) and IL-6 production." (PMID 37998336, 2023). "Herein, the refractory respiratory failure in patients with COVID-19 was associated with increased CRP, D-dimers, LDH, Ferritin, HMGB1, and IL-33, as well as higher numbers of circulating neutrophils, higher plasma levels of IL-6 and IL-10, and diminished numbers of lymphocytes and platelets." (PMID 37604833, 2023). "Therefore, the hsa-circ-0000479/hsa-miR-149-5p/IL-6 RIG-I axis could serve as a promising therapeutic target in the treatment of COVID-19." (PMID 37759744, 2023). "Since the booster campaign was initiated during the study period, and the pandemic continued, we cannot be sure whether or not the observed increase in IL-6 concentrations was caused by COVID-19 vaccination or re-infection." (PMID 36835948, 2023). "In addition, TGFβ1, TGFβ3, IL-6, and IL-10 may be influential biomarkers of COVID-19 severity during the early phase of infection, whereas Th2 cytokines, IL-4 and IL-13, may be markers of persisting severity." (PMID 37569646, 2023). "Another hypothesis for the cardiac involvement in COVID-19 implicates the systemic release of pro-inflammatory cytokines (e.g., IL-1, IL-6, TNF-α, IFN-γ, and MIP) and the subsequent “cytokine storm” as the main culprit with subsequent increased vascular wall permeability and myocardial edema." (PMID 36371548, 2023). "Pre-existing increased IL-6 levels may contribute to chronic fatigue symptoms, but there was no increased risk in individuals with mild COVID-19 compared with uninfected individuals." (PMID 36995412, 2023). "Consequently, this much greater percentage of Roma patients with severe COVID-19 who had increased IL-6 levels at admission might explain why these patients also had persistently elevated inflammatory markers, such as CRP and ESR, upon admission." (PMID 36836429, 2023). "Hence, the evaluation of the influence of polymorphisms in key genes of the IL-6 pathway, namely IL6, IL6R, and IL6ST, may provide valuable prognostic/predictive markers for COVID-19." (PMID 37243282, 2023). "Furthermore, and highlighting the translational relevance of our findings, galectin-9 plasma levels have been shown to correlate with elevated cytokines in COVID-19 patients and addition of recombinant galectin-9 induced IL-6 and TNFα secretion in those patients." (PMID 37755527, 2023).
COVID-19 (continued). "In our study, critical COVID-19 groups also exhibited significant positive correlations of U-CysLT values with several systemic inflammatory markers and parameters, namely with the proinflammatory cytokines IL-6 and TNF-α, with CRP and with total leukocytes, neutrophils, eosinophils and NMR ratio." (PMID 36617343, 2023). "Therefore, the efficacy and safety of IL-6 monoclonal antibodies in the treatment of MAS in COVID-19 and in the treatment of COVID-19 itself need to be more fully evaluated through further prospective and well-designed clinical studies with larger sample sizes and long-term follow-up." (PMID 37483597, 2023). "There is evidence that individuals with an early hyperinflammatory phenotype and organ damage in the second week following the beginning of symptoms may benefit primarily from inhibiting the IL-6 in terms of treating this sort of excessive inflammatory response in COVID-19." (PMID 36851766, 2023). "However, the relationship between the level of Il-6 and other interleukins and the risk of thrombosis in COVID-19 patients has not been confirmed." (PMID 37373613, 2023). "Similarly, another study confirmed that several serum pro-inflammatory mediators including IL-2R, IL-6, IL-10, and TNFα are increased in severe (n = 11) compared to moderate (n = 10) COVID-19 patients, while serum IFNγ levels were decreased negatively correlating with disease severity." (PMID 36941580, 2023). "However, our work suggests that, in contrast to COVID-19 (and perhaps bacterial sepsis), those with genetically proxied reduced IL-6 signaling do not have altered risk of severe disease." (PMID 36801374, 2023). "Severe forms of COVID-19 are driven by a dysregulated inflammatory reaction, also called “cytokine storm”, characterized by high systemic levels of cytokines, including tumor necrosis factor α (TNFα), interleukine-1 (IL-1), interleukine-6 (IL-6), and interferon γ (IFNγ)." (PMID 37108440, 2023). "One of their COVID-19 patients developed transient fever and IL-6 and IL-8 storm four hours after phage inhalation; such reaction might be a result of triggering human immune responses directly by antigens of therapeutic phages or indirectly via the rapid lysis of the targeted bacteria." (PMID 37627705, 2023). "Moreover, the levels of specific peripheral biomarkers that are routinely used in clinical practice for AD diagnosis—such as total tau protein in association with IL-6, Neurofilament Light Chain (NFL) and Glial Fibrillary Acidic Protein (GFAP)—are elevated in the CSF and serum of COVID-19 patients." (PMID 37998336, 2023). "However, the same study showed that plasma IL-6 levels present a more specific biomarker of neurological deficits after COVID-19 since elevation of IL-6 was observed specifically in neuro-long COVID-19 as compared to long COVID-19 without neurological symptoms." (PMID 37008787, 2023). "Next, the levels of interleukin 6 (IL6) and lymphocyte subsets in COVID-19 patients from our hospital were analyzed to verify whether there were abnormalities in interleukin and immune cells in COVID-19 patients with myocardial injury." (PMID 37564653, 2023). "It simultaneously downregulated the expression of IL-6, a cytokine deeply involved in uncontrolled inflammation in chronic inflammatory and autoimmune diseases, cancer, and the cytokine storm induced by viral diseases such as coronavirus disease 2019 (COVID-19)." (PMID 37514430, 2023). "Additionally, deferoxamine reduces IL-6 expression, which is an important inflammatory factor produced in COVID-19, therefore, it may be the candidate therapeutic against COVID-19-mediated liver injury." (PMID 37726282, 2023). "The combined models revealed that while the interaction between periodontitis and COVID-19 did not have significant effect on IL-6 levels, the main effect of COVID-19 was significantly associated with serum and salivary IL-6 levels (P values: 0.002 and 0.004, respectively)." (PMID 37568161, 2023).
COVID-19 (continued). "In addition, the results show an increase in the number of tests for biomarkers used for the evaluation and monitoring of COVID-19 inpatients (IL-6, D-dimer, troponin, arterial blood gases and ferritin), which even increased in 2021 with respect to 2020 for IL-6 and ferritin." (PMID 37363429, 2023). "Moreover, vitamins D and A, selenium, flavonoids, zinc, and unsaturated fatty acids can alleviate inflammatory response in patients with COVID-19 via inhibiting the activation of nuclear factor kappa-B (NF-κB), hence reducing the production of pro-inflammatory cytokines, such as IL-6 and TNF-α." (PMID 38156008, 2023). "Several studies have demonstrated the alleviative and therapeutic effects of GCs on COVID-19 due to their role in inhibiting dysfunctional systemic inflammation, reducing inflammatory-coagulant-fibroproliferative effects, and rapidly decreasing C-reactive protein and interleukin-6 (IL-6) levels." (PMID 38274101, 2023). "In conclusion, the contemporary changes in IL-6, its receptors’ concentrations, and the consequent increased signal transduction, together with a high CCI score as a risk factor, are closely associated with mortality and unfavorable outcomes in COVID-19 infected patients." (PMID 37887780, 2023). "It was clearly demonstrated that treating moderate COVID-19 cases with IFN-α2b could accelerate viral clearance while maintaining adequate levels of circulating pro-inflammatory cytokines such as IL-6 and CRP (C-reactive protein) to strengthen the patients’ immunity against the disease." (PMID 37108513, 2023). "Additionally, IL-1β, along with IL-6 and TNF, has been associated with post-COVID-19 sequelae." (PMID 38090572, 2023). "More severe COVID-19 in hospitalized patients is associated with increased inflammation with higher IL-6, D-dimer, Ferritin and LDH with greater risk of VTE, admission to the ICU, and a higher mortality rate compared to hospitalized patients with less severe COVID-19." (PMID 37400813, 2023). "Therefore, in the context of COVID-19 cytokine storm and severe disease, histamine produced by MCs may induce the appearance of the microvascular leakage, proteases, and IL-6 that can degrade matrix." (PMID 36544127, 2022). "The observations from this study allowed us to hypothesize that the infusions of tocilizumab may not reduce the elevated level of interleukin-6, and hence may not be a significant therapeutic for reducing in-hospital mortality associated with COVID-19." (PMID 36705224, 2022). "In patients with active severe COVID-19 and elevated IL-6 levels, regardless of acute myocardial injury/strain and concomitant QT-prolonging risk factors, QTc was significantly prolonged and rapidly normalized in correlation with IL-6 decrease." (PMID 35665254, 2022). "IL-6 is an important functional marker of cellular senescence, and the age-dependent increase in IL-6 amplifier may correspond to the age-dependent increase in COVID-19 mortality." (PMID 35270015, 2022). "Another reason for the high death rate of COVID-19 in patients with dementia is the cytokine storm, where it has been shown that dementia patients have elevated proinflammatory cytokines, such as tumor necrosis factor-alpha, interleukin-1, and interleukin-6, which increases the death rate." (PMID 35215217, 2022). "In this research, we identified that advanced age, IFN-α, IL-8, and IL-6 have been identified as potential prognostic predictors of COVID-19 outcomes by multiple models in our research, which indicated that these cytokines might play a vital role in the progression of SARS-CoV-2." (PMID 36466533, 2022). "However, although some studies have concluded that the combination of hydroxychloroquine and azithromycin does not contribute significantly to arrhythmias, there is evidence that COVID-19 patients with high levels of IL-6 are more likely to develop arrhythmias when this treatment is used." (PMID 36135437, 2022).